STKLD1 (serine/threonine kinase like domain containing 1)
Synonyms: C9orf96; SGK071; MGC43306; Sk521
Tractability: Small molecule: it belongs to a druggable protein family.
Gene: Protein-coding gene on chromosome 9 (133,376,366 to 133,406,096, forward strand). Ensembl gene ENSG00000198870.
Gene Ontology:
Molecular function: protein serine/threonine kinase activity; ATP binding; protein kinase activity
Genetic constraint (gnomAD): Loss-of-function variants: 75 observed, 77.07 expected, observed/expected ratio (o/e) 0.97, 90% interval 0.81 to 1.18. The upper end of that interval is the gene's LOEUF score, 1.18, which puts it in group 5 of 6, group 1 being the genes least tolerant of losing a copy. Missense variants: 827 observed, 856.84 expected, observed/expected ratio (o/e) 0.97, 90% interval 0.91 to 1.02. Synonymous variants: 383 observed, 357.22 expected, observed/expected ratio (o/e) 1.07, 90% interval 0.99 to 1.17.
Homologues: Orthologues: chimpanzee STKLD1 (99% identical), macaque STKLD1 (89% identical), dog STKLD1 (68% identical), guinea pig STKLD1 (59% identical), rat Stkld1 (58% identical), mouse Stkld1 (57% identical), pig STKLD1 (53% identical).